TRPA1 (transient receptor potential cation channel subfamily A member 1)
Diseases named in the same sentence as TRPA1 in open-access papers (continued):
Sharing a sentence is not in itself a finding about the gene and the disease.
atopic dermatitis (25 papers, 2015 to 2025). "Previous studies have implicated TRPA1 in chronic itch associated with atopic dermatitis, TRPA1-deficient mice exhibit reduced scratching behavior following AEW treatment." (PMID 41451134, 2025). "The role of TRPA1 has been highlighted in several pathways involved in chronic allergic itch, including the release of atopic dermatitis-associated cytokines from keratinocytes via a Th2-cell-neuronal mechanism, such as the pruritogenic cytokine IL-31." (PMID 35562920, 2022). "Scratching induced by IL-13 or IL-31 in atopic dermatitis models was reduced in TRPA1-deficient mice or by TRPA1 inhibition." (PMID 31547502, 2019). "MIT also presents TRPA1 mediated effects in vivo as MIT‐induced paw edema and IL‐4 expression in MIT‐induced allergic dermatitis were downregulated in TRPA1‐defcient mice." (PMID 40329600, 2025). "IL-31 has been shown to upregulate TRPA1 transcription and expression in itchy lesional skin in atopic dermatitis." (PMID 36613861, 2022). "Other potential novel treatments that antagonize the TRPA1 receptor include HC-030031, a TRPA1 antagonist that has been found to decrease itch in mouse models of atopic dermatitis, oxazolone and urushiol exposed mice, and LTB4-induced itch." (PMID 36613861, 2022). "Increased interleukin-31 (IL-31) is found in many itchy conditions including atopic dermatitis and cutaneous T-cell lymphoma, and is thought to contribute to itch sensation through modulation of TRPA1." (PMID 36613861, 2022). "Semiquantitative evaluation of the density of CB2R, GPR55, TRPV1, and TRPA1 immunoreactivity in different cellular elements of the skin of dogs with atopic dermatitis (AD-dogs)." (PMID 36187821, 2022). "In an IL-13-induced mouse model of atopic dermatitis, blocking the TRPA1 led to a reduction of the scratching response." (PMID 34439832, 2021). "Further, in an oxazolone-induced atopic dermatitis model, the expression of IL-6 was significantly decreased in skin samples from TRPA1 KO mice compared to WT mice." (PMID 33374841, 2020). "To investigate the molecular mechanisms behind DINP exacerbated allergic dermatitis, we investigated the expression of TRPA1 in the skin of ears after the mice were exposed to DINP by oral gavage and sensitized with FITC." (PMID 28240277, 2017). "This work also found that blocking TRPA1 by HC030031 effectively prevented the development of allergic dermatitis resulting from oral exposure to DINP and/or FITC-sensitized mice." (PMID 28240277, 2017). "In lesioned skin of human atopic dermatitis patients, TRPA1 expression is increased in dermal afferent fibers, dermal cells, and mast cells." (PMID 25640188, 2015). "In a mouse model of atopic dermatitis generated by overexpression of IL-13, TRPA1 expression is also increased in afferent fibers, dorsal root ganglia, and mast cells in a manner similar to that observed in human patients." (PMID 25640188, 2015). "TRPA1 plays a crucial role during atopic dermatitis (AD) pathogenesis in mice." (PMID 36875034, 2023). "LTB4 is released by white blood cells and acts as a potent chemoattractant to neutrophils and other inflammatory cells—it is found to be increased in atopic dermatitis and psoriasis, and contributes to itch by acting on specific GPCRs that then activate downstream TRPA1 channels." (PMID 36613861, 2022). "A TRPA1-dependent pathway of itch in atopic dermatitis has been shown in an IL-3-induced mouse model, where a correlation between increased scratching behavior and TRPA1 expression in mast cells, dermal sensory nerve fibers, and cell bodies of DRG neurons has been observed." (PMID 35562920, 2022). "Additionally, when TRPA1 is knocked out, as demonstrated by atopic dermatitis mouse models, the mice were found to have a decreased scratching response." (PMID 36613861, 2022). "In addition, TRPA1 was upregulated in sensory neurons and TRPA1 antagonists reduced itch behavior in an interleukin 13-overexpressing transgenic model of atopic dermatitis." (PMID 27983625, 2016).
atopic dermatitis (continued). "In addition, TRPA1 has been reported to promote the inflammatory response and itch in models of allergic contact dermatitis, atopic dermatitis and cytokine-induced itch, while a protective role has been suggested for TRPA1 in the imiquimod-induced model of psoriasiform dermatitis." (PMID 33805042, 2021). "In addition to our data that TRPA1 is an inflammation-inducible gene and supports inflammatory responses, TRPA1 has been shown to play a role in murine models of allergic contact dermatitis and atopic dermatitis." (PMID 33805042, 2021). "In mouse models with atopic dermatitis, knocking out TRPA1 and HTR7 reduced lesions and scratching in HTR7 and TRPA1 knockout mice with atopic dermatitis." (PMID 36613861, 2022). "TRPA1 can be activated by environmental irritants, and is involved in cutaneous inflammatory diseases, including allergic dermatitis, UVB-induced injury, and atopic dermatitis; but evidence specific to KCs TRPA1 was limited." (PMID 36157074, 2022). "Another mouse model of atopic dermatitis, such as that induced by 2,4-dinitrochlorobenzene (DNCB), implicates TRPA1 activation." (PMID 35562920, 2022). "In accordance with the results shown in the rodent model, patients with atopic dermatitis display increased expression of TRPA1 in both pruritic and non-pruritic skin." (PMID 31003539, 2019).
Headache (24 papers, 2012 to 2025). Cephalgia, or pain sensed in various parts of the head, not confined to the area of distribution of any nerve. "Environmental irritants that activate TRPA1 have been shown to trigger migraine headaches in susceptible individuals." (PMID 34122137, 2021). "In summary, endothelial TRPA1 activation exerts a protective effect on neurons by regulating cerebral blood flow, but the activation of neuronal TRPA1 can cause harmful brain symptoms and contribute to conditions such as headaches and age-related cognitive decline." (PMID 39273183, 2024). "An environmental TRPA1 agonist named umbellulone, the scent of the Californian laurel, has been reported to causes an increase in meningeal blood flow when inhaled by rats and can cause headaches in sensitive persons." (PMID 35216445, 2022). "Expressed on Aδ and C afferent fibers, TRPA1 transduces pain from a broad array of irritants, both food (e.g., allyl isothiocyanate in mustard) and chemical (e.g., formaldehyde) and is thought to be implicated in the pathogenesis of headache." (PMID 33799975, 2021). "Although the mechanisms whereby environmental irritants cause headache remain largely unknown, activation of TRPA1 by mechanical or chemical stimuli causes CGRP to be released and increases cerebral blood flow." (PMID 33799975, 2021). "Transient receptor potential ankyrin 1 (TRPA1) is known to play a role in acute and inflammatory nociception, neuropathic pain, cancer-related pain, migraine headache, and dysfunctional pain." (PMID 39063144, 2024). "TRPA1 antagonism in molecular models has shown to be capable of alleviating hyperalgesia, neuropathic pain, arthritic pain, postoperative pain, migraine headache, and visceral pain." (PMID 39063144, 2024). "TRPA1 has been demonstrated to play key roles in acute and inflammatory nociception, neuropathic pain, cancer-related pain, migraine headache, and dysfunctional pain by various mechanisms." (PMID 39063144, 2024). "TRPA1 was originally identified as a ‘nociceptive’ receptor activated by thermal and mechanical stimuli; however, more and more headache-inducing factors have also been revealed to be TRPA1 activators." (PMID 36982450, 2023). "Subsequently, it was shown that umbellulone stimulated TRPA1 and its stimulation in the dura by umbellulone and mustard oil induced headache responses in rats." (PMID 37326902, 2023). "Activating as well as inhibitory effects of TRPA1 agonists have been reported in animal models of headache." (PMID 35216445, 2022). "It is important to clarify that here we are using a rodent model of PMS and it is necessary to conduct more investigation to relate the TRPA1 channels to future new treatments for headache in PMS patients." (PMID 34451927, 2021). "Appropriately, TRPA1 activation in trigeminal nerve endings located in the nasal mucosa are suspected to trigger headache when irritants are inhaled." (PMID 31336748, 2019). "Other compounds, e.g., umbellulone (UMB, which can be found in the leaves of the so-called “headache tree”) were also found to activate TRPA1 and TRPM8, thereby causing severe headaches and cold sensations." (PMID 30087301, 2018). "In the same rat model of acrolein-induced headache used in the present study, systemic pretreatment with the TRPA1 antagonist AP-18 prevented the sensitization of the TVS due to chronic acrolein." (PMID 29430557, 2017). "The transient receptor potential A1 channel (TRPA1) is activated by nasal irritants and thus is a candidate receptor to initiate this headache cascade." (PMID 25077949, 2014). "Nasal administration of acrolein and mustard oil induced meningeal vasodilatation, which was blocked by prior nasal application of a TRPA1 antagonist suggesting a critical role for TRPA1 in environmental irritant-induced headache." (PMID 25077949, 2014).
Headache (continued). "Umbellulone, the most abundant volatile component from the leaves of the headache tree, was found to be a TRPA1 agonist capable of eliciting meningeal blood flow after nasal administration and CGRP release when applied to trigeminal neurons." (PMID 25077949, 2014). "Umbellulone, a monoterpene ketone that is an active constituent of the leaves of Umbrellularia californica, is thought to induce headache via the activation of transient receptor potential cation channel subfamily A, member 1 (TRPA1) channels in trigeminal nerve fibers and the release of CGRP." (PMID 40708951, 2025). "Here, we review the functional relevance of TRPA1 in headaches and its therapeutic potential, mainly focusing on its role in the development of hypersensitivity, referring to its altered expression in pathological conditions, and its functional interaction with other TRP channels." (PMID 36982450, 2023). "Several clinical observations have indicated that different agents (e.g., herbs, food, environments) have the ability to influence migraine headaches via the modulation of subclasses of TRP superfamilies (TRP-ankyrin 1—TRPA-1; TRP-vanilloid 1—TRPV-1; TRP-melastatin 8—TRPM-8)." (PMID 36835524, 2023). "In contrast, compounds known for their anti-headache properties were shown to desensitize TRPA1." (PMID 31336748, 2019). "This was the first in a line of publications by these authors documenting and interaction between environmental irritants and TRPA1 that may lead to headaches following exposure." (PMID 30970581, 2019). "Similarly, the well-known headache inducer, glyceryl trinitrate, targets TRPA1 in TG neurons to generate periorbital oxidative stress and mechanical allodynia." (PMID 31336748, 2019). "Other environmental stimulants such as cigarette smoke, chlorine, formaldehyde, and pollution are also thought to induce headache via their activation of TRPA1 or other TRP channel subtypes such as transient receptor potential vanilloid 1 (TRPV1) or transient receptor potential menthol 8 (TRPM8)." (PMID 28335379, 2017). "Case studies have reported that inhalation of TRPA1 agonists can trigger headache in people." (PMID 28091820, 2017). "TRPA1 may be involved in the excitation of dural afferent neurons resulting in headaches." (PMID 37326902, 2023). "TRPA1 senses oxidative stress products, sends the signal to sensory neurons, induces CGRP release, and activates the trigeminovascular system to evoke headaches." (PMID 39064963, 2024). "TRPA1 may be a central element of the signaling pathway from oxidative stress and NO production to CGRP release, which may play a critical role in headache induction." (PMID 39064963, 2024). "It was concluded that TRPA1 channel contributed to the excitation of dural afferent neurons and the subsequent activation of the headache circuit, providing an anatomical basis for the functional significance of TRP channels in headache pathophysiology." (PMID 37326902, 2023). "Together, these experiments provide evidence that acrolein exposure drives changes in CNS lipids that support a working hypothesis that both TRPA1 and TRPV1 activity play a role in the headache induced by acrolein exposure." (PMID 29430557, 2017). "Recent studies have shown that the intranasal administration of TRPA1 agonists stimulates CGRP release and increases meningeal blood flow, suggesting that these events may contribute to the onset of headaches triggered by environmental irritants." (PMID 22971321, 2012). "Therefore, TRPA1 may be a central element of the signaling pathway from oxidative stress and NO production to CGRP release, which may play a critical role in headache induction." (PMID 39064963, 2024). "The reductions of MMA blood flow, TRPV1 and CGRP immunoreactivity, and TRPV1 and TRPA1 mRNA expression, are all consistent with the hypothesis that TRPA1 receptors, co-expressed with TRPV1, play a critical role in environmental irritant-induced headache." (PMID 25077949, 2014).
Headache (continued). "Taken together, our results suggest that TRPV1 and TRPA1 but not TRPM8 channels likely contribute to the excitation of dural afferent neurons and the subsequent activation of the headache circuit." (PMID 22971321, 2012).
diabetes (22 papers, 2013 to 2024). "TRPA1 is activated to treat enteritis, cardiovascular, cerebrovascular inflammatory diseases, and inflammation caused by diabetes, obesity, kidney damage, and sepsis." (PMID 36875034, 2023). "The involvement of TRPA1 in pain perception makes it a potential therapeutic target for the treatment of other comorbid conditions associated with diabetes." (PMID 34912298, 2021). "In chronic inflammation caused by diabetes, cancer etc., ROS levels increase systemically and modulate TRPA1 neuronal functions and cause debilitating neuropathic pain." (PMID 33424587, 2020). "We have previously shown that twice weekly treatment with recombinant human (rh)VEGF-A165b reverses both pain and neuronal terminal loss during experimental diabetes, and sensitisation of sensory neuronal TRPA1-evoked responses." (PMID 29930087, 2018). "Taking all together, modulation of central as well as peripheral TRPA1 channels can be a novel therapeutic strategy to protect against metabolic adversities associated with NPDs, out of which the major ones are weight gain and diabetes." (PMID 34912298, 2021). "In the long term, release of diabetes-generated compounds may cause a sustained influx of calcium ions through TRPA1 channels in nerve terminals." (PMID 30388732, 2018). "In diabetes, TRPA1 regulates insulin secretion and sensitivity, indicating its therapeutic potential." (PMID 39273183, 2024). "TRPA1 antagonism has been observed to decrease mechanical allodynia and hypersensitivity in a rodent model of diabetes induced by streptozotocin." (PMID 37781093, 2023). "It was also indicated that TRPA1 agonists such as cinnamaldehyde improve diabetes in vivo through glucose transporter (GLUT4) translocation in peripheral tissues." (PMID 35455971, 2022). "Collectively, this evidence suggests a strong involvement of TRPA1 agonist cinnamaldehyde in controlling appetite and being a promising candidate to manage diabetes and obesity." (PMID 34912298, 2021). "Prolonged blocking of TRPA1 has even had a disease-modifying effect in PDN, as shown by a delayed loss of a nociceptive nerve endings and their function in experimental diabetes." (PMID 30388732, 2018). "Antagonism of TRPA1 by A-967079 was reported to reduce free methylglyoxal and alleviate diabetic neuropathic pain." (PMID 27589700, 2016). "The present study investigated the effects of Andaliman fruit extract on tumor necrosis factor-alpha (TNF-α) and transient receptor potential ankyrin-1 (TRPA-1) levels in type 2 diabetes mellitus (T2DM) mouse models induced with streptozocin (STZ) and a high-fat diet (HFD)." (PMID 39101085, 2024). "In this context and the context of the role of epigenetic modifications of the TRPA1 gene in pain transmission, the results obtained on the effect of histone acetylation on TRPA1 expression in diabetes may be important." (PMID 37326902, 2023). "TRPA1 expressed on oligodendrocytes might play a role also in the methylglyoxal-driven hippocampal damage observed in animals with experimental diabetes." (PMID 30388732, 2018). "In addition to inflammatory responses, a series of reports suggest that TRPA1 antagonists are useful to treat neuropathic pain, such as diabetic neuropathic pain and nerve injury induced pain." (PMID 27589700, 2016). "Additionally, methylglyoxal, a reactive metabolite that accumulates intracellularly in diabetes and chronic kidney disease, is able to directly activate TRPA1 resulting in a painful neuropathy in mice." (PMID 25640188, 2015). "In addition, data suggest that CBS, TRPA1, TRPV1 and TRPC channels could be potential targets for the treatment of peripheral neuropathy associated with diabetes." (PMID 30602386, 2019). "Although acute administration of MG identified a potential role for TRPA1 as a sensor of elevated MG levels, it is not an experimental situation that accurately reflects the long-lasting, widely increased MG levels associated with hyperglycemia in diabetes." (PMID 24167592, 2013).